CPN2 (carboxypeptidase N subunit 2)
Description:
The 83 kDa subunit binds and stabilizes the catalytic subunit at 37 degrees Celsius and keeps it in circulation. Under some circumstances it may be an allosteric modifier of the catalytic subunit.
Synonyms: ACBP
Tractability: Small molecule: it belongs to a druggable protein family. Antibody: its Gene Ontology location is reachable by antibodies, with high confidence; UniProt places it where antibodies can reach, with medium confidence; UniProt predicts a signal peptide or a membrane-spanning region.
Gene: Protein-coding gene on chromosome 3 (194,339,630 to 194,351,401, reverse strand). Ensembl gene ENSG00000178772.
Subcellular location: Secreted
Pathways (Reactome):
Immune System: Regulation of Complement cascade
Gene Ontology:
Molecular function: enzyme regulator activity; signaling receptor activity
Biological process: protein stabilization
Cellular component: blood microparticle; extracellular exosome; extracellular region; plasma membrane
Genetic constraint (gnomAD): Loss-of-function variants: 1 observed, 1.52 expected, observed/expected ratio (o/e) 0.66, 90% interval 0.21 to 1.83. That is too few expected variants to judge how well the gene tolerates losing a copy. Missense variants: 596 observed, 674.34 expected, observed/expected ratio (o/e) 0.88, 90% interval 0.83 to 0.95. Synonymous variants: 326 observed, 321.97 expected, observed/expected ratio (o/e) 1.01, 90% interval 0.92 to 1.11.
Homologues: Orthologues: chimpanzee CPN2 (99% identical), macaque CPN2 (93% identical), pig CPN2 (77% identical), rabbit CPN2 (77% identical), dog CPN2 (76% identical), mouse Cpn2 (67% identical), rat Cpn2 (67% identical), guinea pig CPN2 (64% identical), Drosophila melanogaster CG18095 (22% identical), Drosophila melanogaster CG7509 (22% identical), Caenorhabditis elegans sma-10 (20% identical), Caenorhabditis elegans lron-9 (19% identical), and 3 more. Paralogues in human: TRIL (31% identical), CHADL (26% identical), LRIG1 (26% identical), LRIG3 (25% identical), LRIG2 (25% identical), LGR6 (23% identical), LGR5 (22% identical), LGR4 (22% identical), LRRC24 (19% identical), LRRTM2 (19% identical), LRG1 (18% identical), LRRC26 (15% identical), and 10 more.
Diseases named in the same sentence as CPN2 in open-access papers:
CPN2 is named in the same sentence as 15 diseases in open-access papers, as found by Europe PMC text mining. Sharing a sentence is not in itself a finding about the gene and the disease. The quoted sentences say what the papers report.
breast carcinoma (3 papers, 2022 to 2023). "The expression patterns of SYF2 and CPN2 in other breast cancer studies and in studies of other tumor types were both opposite to the findings of this study." (PMID 36294892, 2022). "In recent years, emerging evidence suggested that CPN2 performs a crucial biological function in the invasion and migration of breast cancer and can be used as a biomarker for effective diagnosis and treatment of breast cancer." (PMID 35686102, 2022).
liver disease (2 papers, 2023 to 2024). "By training random forest models, a biomarker panel comprising KNG1, F11, KLKB1, CAPNS1, CDH1, CPN2, NME2, was identified by feature selection for liver disease detection." (PMID 39207047, 2024). "In addition, many novel liver disease biomarkers were discovered, such as EGF-containing fibulin-like extracellular matrix protein 1 (EFEMP1), SAA2, CPN2, ANPEP, TGFBI, and FGG." (PMID 37209815, 2023).
acute myocardial infarction (1 paper, 2021). Necrosis of the myocardium, as a result of interruption of the blood supply to the area. "Serum levels of CPN2 were not investigated in patients with stroke, but increased concentrations were found in patients with acute myocardial infarction." (PMID 34975707, 2021).
lung adenocarcinoma (1 paper, 2022). A carcinoma that arises from the lung and is characterized by the presence of malignant glandular epithelial cells. "Our findings suggested that the upregulation of CPN2 is associated with a worse clinical outcome in lung adenocarcinoma and cancer-related pathways, which laid the foundation for further research on CPN2 during carcinogenesis." (PMID 35686102, 2022). "It suggested that CPN2 can be used as a potential tumor marker for the prognosis of lung adenocarcinoma in early stage." (PMID 35686102, 2022). "The results showed that the transcription level of CPN2 was significantly increased in the tumor tissues of lung adenocarcinoma patients compared to the adjacent normal tissues in The Cancer Genome Atlas cohort (P < 0.05)." (PMID 35686102, 2022). "Further univariate and multivariate Cox regression analyses showed that CPN2 may act as an independent prognostic factor in patients with lung adenocarcinoma (P < 0.05)." (PMID 35686102, 2022). "Our study aimed to explore the potential role and functions of CPN2 in lung adenocarcinoma." (PMID 35686102, 2022). "However, the clinical significance and biological functions of CPN2 in lung adenocarcinoma remain unclear." (PMID 35686102, 2022). "The gene set enrichment analysis showed that a higher expression of CPN2 may participate in mTOR, TGF-BETA, NOTCH, TOLL-like-receptor, WNT, and MAPK signaling pathway in lung adenocarcinoma." (PMID 35686102, 2022).
lung carcinoma (1 paper, 2022). "For the cellular functional experiments, the loss of function assay was performed using CPN2 silencing in lung cancer cell lines." (PMID 35686102, 2022). "In order to evaluate the diagnostic efficacy of CPN2 in lung cancer patients, the receiver operating characteristic (ROC) curve was used to test the hypothesis." (PMID 35686102, 2022). "Our study found, for the first time, that CPN2 acted as a novel oncogene and played an important role during the process of lung cancer." (PMID 35686102, 2022). "The colony formation assay showed that the CPN2 knockdown dramatically inhibited the clones’ number of lung cancer cells." (PMID 35686102, 2022). "CPN2 expression was significantly upregulated in lung cancer tissues compared with adjacent normal tissues (P < 0.01)." (PMID 35686102, 2022). "In order to solidly establish the role of CPN2 in lung cancer, we performed the rescue experiment with CPN2 cDNA after the siRNA transfections to rescue the phenotype." (PMID 35686102, 2022). "To evaluate the clinical significance of CPN2, we used the Kaplan–Meier public database to analyze the relationship between CPN2 expression and the clinical outcomes of lung cancer patients." (PMID 35686102, 2022). "To assess the impact of CPN2 expression on lung cancer, we assembled gene expression datasets from TCGA cohort." (PMID 35686102, 2022). "Transwell migration and Matrigel invasion assays showed that CPN2 downregulation significantly inhibited the migratory and invasive capabilities of lung cancer cells, respectively." (PMID 35686102, 2022). "Clinical factor and CPN2 expression in lung cancer patients." (PMID 35686102, 2022). "In order to evaluate the value of CPN2 protein expression in the diagnosis of lung cancer patients, the ROC curve was used to test the hypothesis." (PMID 35686102, 2022). "Importantly, the high expression of CPN2 showed worse survival only in stages I and II, but not in stages III, suggesting that CPN2 expression is an independent prognostic biomarker for lung cancer in an early stage." (PMID 35686102, 2022).
Obesity (1 paper, 2024). Accumulation of substantial excess body fat. "Notably, CPN2 (carboxypeptidase N Subunit 2), F5 (coagulation factor V), ECM1 (extracellular matrix protein 1), KNG1 (kininogen 1), FN1 (fibronectin 1), and GPLD1 (glycosylphosphatidylinositol-specific phospholipase D1) were found to be elevated in both human and mouse sEVs under obesity conditions." (PMID 38402239, 2024).
squamous cell carcinoma (1 paper, 2022). A carcinoma arising from squamous epithelial cells. "The subgroup analysis showed that a higher CPN2 predicted a worse survival outcome in the adenocarcinoma group (P < 0.001), but not in the squamous cell carcinoma group (P > 0.05)." (PMID 35686102, 2022).
Stroke (1 paper, 2021). Sudden impairment of blood flow to a part of the brain due to occlusion or rupture of an artery to the brain. "Based on our data, we suggest that CPN2, FXII, PLG, MASP1, APCS, PON1, and CA1 for IS and FBLN1 and GRN for ICH should be further scientifically pursued as potential stroke blood biomarkers." (PMID 34975707, 2021).
cancer (2 papers, 2022 to 2024). A tumor composed of atypical neoplastic, often pleomorphic cells that invade other tissues. "CPN2, a pleiotropic regulator of inflammation, is also associated with the occurrence and development of multiple cancer types." (PMID 39207047, 2024). "Integrating the results of GSEA and co-expression gene enrichment, we propose that CPN2 may play a vital role through cancer-related pathways." (PMID 35686102, 2022). "Besides this, CPN2 could participate in some cancer-related pathways." (PMID 35686102, 2022).
tumor (2 papers, 2022). "In LUAD patients, CPN2 expression was significantly upregulated in tumor tissues both in paired and unpaired samples compared with adjacent normal tissues (P < 0.01)." (PMID 35686102, 2022). "The tissue microarray analysis found that CPN2 protein expression was significantly positively correlated with node status and tumor stage as well as tumor malignancy (P < 0.05)." (PMID 35686102, 2022). "Combining the results of our study and related literature reports, we speculated that CPN2 promoted tumor cell proliferation, invasion, and metastasis and inhibited apoptosis through Akt and the fibrillar collagen family or (and) this key pathway in the critical stage of LUAD." (PMID 35686102, 2022).
CPN2 also shares sentences with these, for which no sentence is quoted: adenocarcinoma (1 paper); COVID-19 (1); preeclampsia (1); rheumatoid arthritis (1); Sézary syndrome (1).